ENSG00000285283 (novel protein)
Gene: Protein-coding gene on chromosome 11 (31,812,391 to 32,104,665, forward strand). Ensembl gene ENSG00000285283.
Genetic constraint (gnomAD): Loss-of-function variants: 9 observed, 23.44 expected, observed/expected ratio (o/e) 0.38, 90% interval 0.23 to 0.67. Missense variants: 189 observed, 255.41 expected, observed/expected ratio (o/e) 0.74, 90% interval 0.66 to 0.83. Synonymous variants: 72 observed, 89.53 expected, observed/expected ratio (o/e) 0.8, 90% interval 0.66 to 0.98.